MCU (mitochondrial calcium uniporter)
Diseases named in the same sentence as MCU in open-access papers (continued):
Sharing a sentence is not in itself a finding about the gene and the disease.
colorectal cancer (16 papers, 2019 to 2025). A primary or metastatic malignant neoplasm that affects the colon or rectum. "Upregulation of the mitochondrial calcium uniporter (MCU) has been shown to facilitate colorectal cancer cell growth, but the contributions of MCU-regulatory proteins are not known." (PMID 39466877, 2024). "In colorectal cancer, MCU was targeted by miR-138-5p, with downregulation of miR-138-5p leading to increased MCU expression." (PMID 38632642, 2024). "Another study suggested that MCU interacts with RIPK1 to promote colorectal cancer cell proliferation by increasing mitochondrial Ca2+ uptake and energy metabolism." (PMID 37885995, 2023). "The downregulation of MCU and subsequent reduction of mtCa2+ uptake correlated with resistance to apoptosis of colorectal cancer cell lines." (PMID 32914752, 2020). "Furthermore, Piezo1 promotes colorectal carcinoma metastasis by increasing mitochondrial calcium uniporter (MCU) transcription that elevates mitochondrial membrane potential, activating the HIF-1α/VEGF pathway." (PMID 36230880, 2022). "However, it remains unclear whether MCU regulates mitochondrial Ca2+ uptake to promote cell growth in colorectal cancer (CRC)." (PMID 32371956, 2020). "SIRT1 inhibition increases the acetylation of mitochondrial calcium uniporter (MCU), leading to mitochondrial Ca2+ overload and depolarization, and ultimately to apoptosis in colorectal cancer (CRC) cells." (PMID 39479446, 2024). "In particular, Piezo1 promotes the proliferation and migration of human colorectal cancer (SW-480 and HCT-116) cells via mitochondrial calcium uniporter (MCU), hypoxia-inducible factor (HIF)-1ɑ and vascular endothelial growth factor (VEGF)." (PMID 36158191, 2022). "In colorectal cancer, increased expression of MCU leads to enhanced uptake of mitochondrial Ca2+, promoting mitochondrial biogenesis by inhibiting TFAM phosphorylation, ultimately accelerating the proliferation of colorectal cancer cells." (PMID 39164792, 2024). "Moreover, the mitochondrial tumor suppressor Fus1 diminishes MCU expression and the expression of NCLX affects colorectal cancer growth and metastasis." (PMID 33614647, 2021).
colon carcinoma (13 papers, 2017 to 2025). "The expression of this miRNA is upregulated in human colon cancers where MCU expression is accordingly downregulated, and this correlates with apoptotic death resistance." (PMID 37759703, 2023). "Recent studies have found that MCU is highly expressed in colon cancer, hepatocellular carcinoma, and pancreatic ductal adenocarcinoma." (PMID 37885995, 2023). "JC-1 assay revealed that MCU knockdown reduced MMP compared to MCU overexpression in two colon cancer cells." (PMID 32152662, 2020). "MCU expression was lower in high- or low-differentiation colon cancer tissues than adjacent normal tissues, which was confirmed by qRT-PCR and western blotting analysis." (PMID 32152662, 2020). "Contrary to Piezo1, MCU knockdown promoted colon cancer cell viability, migration, motility, and metastasis." (PMID 32152662, 2020). "Second, functional assays were performed to investigate the effects of Piezo1 and MCU on colon cancer cell migration, invasion, and mitochondrial membrane potential." (PMID 32152662, 2020). "MCU activity can be post-translational regulated by the miRNA 25 (miR-25) which expression in colon cancer is inversely regulated: overexpression of miR-25, by downregulating MCU, reduces mitochondrial Ca2+ uptake and protects cells from apoptotic stimuli." (PMID 30011966, 2018). "Classical MCU inhibitors (direct pore blockers) such as ruthenium complexes (ruthenium red and Ru360) have been shown to induce apoptosis in kidney tubular cyst cells and colon carcinoma HCT-116 cells." (PMID 39866241, 2025). "Therefore Piezo1 and MCU are likely to play a role in colon cancer cell metastasis through the Piezo1-MCU-HIF-1α-VEGF pathway." (PMID 36187789, 2022). "In the present study, we found that MCU was down-regulated in colon cancer tissues." (PMID 32152662, 2020). "Overexpressing Piezo1 and silencing MCU could promote colon cancer cell migration and metastasis, reduce mitochondrial membrane potential, and promote each other’s expression." (PMID 32152662, 2020). "Thus, it is unlikely that differences in mitochondrial Ca2+ uptake between normal and colon cancer cells are due to differences in expression of MCU and/or its modulatory regulator MICU1." (PMID 28903423, 2017). "However, a large number of studies showed that MCU downregulation or inhibition increases resistance to apoptosis, in colon cancer cells via the upregulation of miR-25, a microRNA targeting the MCU itself." (PMID 28913175, 2017). "However, down-regulation of MCU expression, mediated by the over-expression of the cancer-related MCU-targeted microRNA, miR-25, has been reported to contribute to apoptosis resistance in colon cancer." (PMID 32825277, 2020). "First, we examined the expression levels of Piezo1 and mitochondrial calcium uniporter (MCU) both in colon cancer tissues and assessed the prognostic value of Piezo1 and MCU in a colon cancer cohort (n = 110)." (PMID 32152662, 2020). "Consistent with previous research, our study showed that HIF-1α expression was attenuated in MCU-silenced HCT-116 and SW-480 cells, indicating that HIF-1α could be a target of MCU in colon cancer." (PMID 32152662, 2020). "Therefore, in our study, we explored the regulatory relationships among Piezo1, MCU, and HIF-1α in colon cancer metastasis." (PMID 32152662, 2020). "As such, miR-25, targeting MCU, was overexpressed in colon cancer cell lines and tumor samples, decreasing MCU expression compared to non-tumorigenic cells." (PMID 29491433, 2018).
hepatocellular carcinoma (13 papers, 2020 to 2024). A malignant tumor that arises from hepatocytes. "The elevation in mitochondrial Ca2+ through MCU overexpression promotes hepatocellular carcinoma (HCC) metastasis through ROS production." (PMID 35490194, 2022). "In hepatocellular carcinoma studies, MCU-dependent mitochondrial Ca2+ uptake promotes metastasis of HCC cells." (PMID 35743109, 2022). "The hepatocellular carcinoma cell line exhibits the role of mitochondrial calcium uniporter, MCU, in EMT and metastasis through the ROS/Nrf/Notch1 pathway." (PMID 35186947, 2021). "In hepatocellular carcinoma (HCC), studies have demonstrated that patients exhibiting high expression of MCU/MiCU2 have a poorer prognosis in terms of overall survival (OS)." (PMID 38911376, 2024). "However, in vitro studies have shown that MCU silencing in HeLa and Hs578T breast cancer, triple-negative breast cancer and hepatocellular carcinoma (HCC) cells drastically inhibits cell migration, motility and invasion without affecting basal proliferation rates or apoptosis levels." (PMID 34070562, 2021). "MCU expression is upregulated in hepatocellular carcinoma (HCC) cells from metastatic samples, with a significant correlation between high MCU expression and poor patient prognosis." (PMID 32059571, 2020). "Similarly, in hepatocellular carcinoma (HCC) cells, the upregulation of MCU and the downregulation of MICU1 led to an increased basal mCa2+ compared to the control cells." (PMID 34307407, 2021).
heart failure (12 papers, 2019 to 2025). Inability of the heart to pump blood at an adequate rate to meet tissue metabolic requirements. "In contrast, most recent studies indicate a positive effect of MCU upregulation in hypertrophy and heart failure." (PMID 38074139, 2023). "Salsolinol ameliorates DOX-induced heart failure by suppressing the mitochondrial calcium uniporter signaling pathway." (PMID 38138580, 2023). "There may also be tissue/cell specific actions here, since in both early- and end-stage pressure overload induction of heart failure, MCU is actually upregulated and MCU inhibition confers cardioprotection." (PMID 36388115, 2022). "In this study, mitochondria calcium uniporter (MCU), dynamin‐related protein‐1 (DNM1L/Drp1) and their relationship with autophagy in heart failure (HF) and CRT are investigated." (PMID 30938090, 2019). "In myocardial samples from patients with heart failure, MICU1 levels and the MICU1/MCU ratio are increased, which might explain the differences in MCU current measured in mitoplasts (i.e., mitochondria stripped of the outer membrane) isolated from myocardial samples of heart failure patients." (PMID 38890208, 2024). "Since the heart samples in the present study represent rather a moderate, though not an end-stage, hypertrophy or heart failure, the increase in MCU expression found may indicate a compensatory stage of hypertrophy." (PMID 38074139, 2023). "Our previous work demonstrated MCU upregulation could promote EADs in heart failure conditions without mPTP openings." (PMID 34721066, 2021). "However, in nonischemic cardiomyopathy, MCU upregulation, together with other electrophysiological remodeling changes in heart failure conditions, can result in an all-or-none behavior or bistability, corresponding to the no EAD and EAD states in AP without mitochondrial depolarization." (PMID 33493168, 2021).
cardiac hypertrophy (8 papers, 2019 to 2025). "In contrast, cardiac‐specific overexpression of MCU maintains Ca2+ homeostasis, preserves contractile function, and prevents cardiac hypertrophy." (PMID 40622073, 2025). "Recently, miR-1 was found to effectively bind to the mitochondrial calcium uniporter (MCU) mRNA to influence mitochondrial Ca2+ flux, contributing to cardiac hypertrophy." (PMID 31766319, 2019). "Another study investigated the role of miR-1 in cardiac hypertrophy by targeting mitochondrial calcium uniporter (MCU), the pore-forming subunit of the mitochondrial Ca2+ uniporter complex (MCUC)." (PMID 31547607, 2019). "MiR-1 is also involved in mitochondrial Ca2+ overload through targeting the mitochondrial calcium uniporter (MCU) mRNA and inhibiting its translation, thereby leading to cardiac hypertrophy." (PMID 34392401, 2021). "Similarly, deletion of MCU did not exhibit any overt baseline phenotype but exacerbated cardiac hypertrophy and cardiomyocyte death in mice subjected to continuous isoprenaline infusion, again demonstrating the importance of stress in revealing knockout phenotypes." (PMID 40279007, 2025).
diabetes (8 papers, 2017 to 2024). "It has been shown, for example, that the development of STZ-induced diabetes lowers the rate of Ca2+ uptake by mice heart mitochondria, and this effect has been revealed to be associated with the decreased expression of MCU." (PMID 31480399, 2019). "Ca2+ is an important regulatory ion and mitochondrial dysfunction caused by the imbalance of mCa2+ homeostasis is considered to be a significant pathological mechanism of diabetes, while MCU/MICU1 is a key molecule that regulates mCa2+ uptake." (PMID 37337224, 2023). "Mice with streptozotocin (STZ) diabetes showed increased expression of MICU1 in the heart but decreased expression of MCU and MCU regulatory factors (such as EMRE, an MCU subunit), leading to mitochondrial Ca2+ uptake, reduced mitochondrial function and decreased heart function." (PMID 37845840, 2024). "However, a critical role emerges for MICU1, the only MCU complex component strongly upregulated during the transition from obesity to diabetes." (PMID 37759703, 2023). "Our findings suggest that changes in MCU expression or activity may contribute to defective insulin secretion in some forms of diabetes." (PMID 32350566, 2020). "Mitochondrial calcium uniporter plays an important role in hyperglycaemia-induced endothelial cell dysfunction and may constitute a therapeutic target to reduce vascular complications in diabetes." (PMID 28777009, 2017).
pancreatic cancer (8 papers, 2017 to 2026). "For example, we have shown that exogenous TGFβ, which is secreted by both tumor cells and cancer‐associated fibroblasts, protects against growth defects in MCU‐knockout pancreatic cancer cells." (PMID 40985275, 2025). "Finally, in pancreatic cancer MCU and MICU1 genes undergo loss of heterozygosity, although whether MCU and MICU1 are oncogenes or tumor suppressor genes still needs to be clarified." (PMID 28740830, 2017). "Overall, these studies suggest that MCU also plays a role in the pathogenesis of pancreatic cancer, in particular the structural subunit EMRE." (PMID 37759703, 2023). "In pancreatic cancer models, MCU expression promotes dependency on exogenous cystine, suggesting that mitochondrial Ca2+ uptake may promote changes in metabolic substrate preferences." (PMID 40985275, 2025). "Moreover, the mitochondrial calcium uniporter (MCU) has emerged as a significant contributor to metastasis and represents a targetable weakness for inducing ferroptosis in pancreatic cancer." (PMID 40427552, 2025). "Focusing on critical regulators, such as FSP1, MCU, and SMAD4, along with leveraging the vulnerabilities linked to ferroptosis, presents a promising avenue for enhancing treatment outcomes in patients with pancreatic cancer." (PMID 40427552, 2025). "Similarly, MCU knockout sensitized pancreatic cancer cells to both gemcitabine and 5‐fluorouracil." (PMID 40985275, 2025). "This suggests that MCU inhibition may not be an appropriate monotherapy target in pancreatic cancer, though co‐inhibition of MCU and TGFβ signaling could be considered." (PMID 40985275, 2025).
Obesity (7 papers, 2018 to 2024). Accumulation of substantial excess body fat. "A critical gap exists in our understanding of the potential role of MCU genetic variants in obesity susceptibility." (PMID 38674446, 2024). "These limitations make it difficult to precisely know how the identified SNPs may be altering MCU expression and/or function to increase susceptibility or protection from obesity." (PMID 38674446, 2024). "This work suggests that mutation in the MCU gene is a causative factor for obesity." (PMID 38674446, 2024). "Our interest in the MCU gene was due to the established link between obesity and dysregulated organelle calcium influx and the important role of MCU in the regulation of mitochondrial calcium homeostasis." (PMID 38674446, 2024). "This is the first analysis of the MCU gene with obesity traits in two racially diverse cohorts from the AoU Research Program." (PMID 38674446, 2024). "Indeed, it has been reported that pharmacological and genetic disruption of MCU in mice ameliorated diet-induced obesity." (PMID 38674446, 2024). "Increased MCU gene expression and/or activity alteration could be a potential clinical biomarker to show a propensity for obesity development in B/AA women." (PMID 38674446, 2024). "Therefore, studies that explore the function of the wild type or mutant MCU complex components during diet-induced obesity, aging, pregnancy, and T2D are needed." (PMID 35805078, 2022). "Taken together, these data suggest that MCU inhibition may represent a promising therapy for prevention of deleterious effects of obesity and metabolic diseases." (PMID 29709004, 2018). "The data suggest that MCU inhibition may represent a promising therapy for prevention of deleterious effects of obesity and metabolic diseases." (PMID 29709004, 2018). "Studies of MCU allelic variants and their association with obesity are not fully understood." (PMID 38674446, 2024). "This suggests that the change in the expression of MCU may not occur at the early stages of obesity, although it is likely to be associated with obesity in the long-term." (PMID 31437152, 2019).
neuroblastoma (6 papers, 2018 to 2022). Neuroblastoma (NB) is the most common solid, extracranial childhood tumor. "Other studies in cardiac and neuroblastoma cells have shown that Ca2+ entry via TRPM2 activates Pyk2/MCU signalling and modulates mitochondrial function and cell survival." (PMID 35269464, 2022). "Decreased expression and activity of MCU in neuroblastoma cells with TRPM2 deletion may contribute to reduced cell cycle progression during G1/S and G2/M through inability to meet increased energy requirements." (PMID 35428820, 2022). "Inhibition of the mitochondrial calcium uniporter phenocopied Miro1 R272Q cytosolic calcium response to Thapsigargin in active neurons, a similar effect was observed during the calcium buffering phase in Miro1 knockdown neuroblastoma cells." (PMID 36533136, 2022). "Reduced MCU expression in KO cells resulted in lower peak mitochondrial Ca2+ uniporter currents and the amount of calcium transported (current-time integral) measured in neuroblastoma mitoplasts and also observed in mitoplasts from TRPM2 knockout myocytes." (PMID 30020827, 2018). "In this line, either MCU overexpression or MCU activation by spermine reversed Pb2+-induced oxidative stress and inhibition of mitochondrial Ca2+ uptake in SH-SY5Y human neuroblastoma cells." (PMID 35052668, 2022). "Results demonstrate that TRPM2 expression protects the viability of neuroblastoma through Src, Pyk2, CREB, and MCU activation, which play key roles in maintaining mitochondrial function and cellular bioenergetics." (PMID 30020827, 2018).